TNF (tumor necrosis factor)
Diseases named in the same sentence as TNF in open-access papers (continued):
Sharing a sentence is not in itself a finding about the gene and the disease.
cancer (continued). "An association between cancer treatment-related symptoms and inflammatory cytokines could be shown, triggered by increased production and synergistic action of IL-1β and TNFα." (PMID 30042333, 2018). "In addition, TNF-α secreted from cancer cells triggers cancer associated fibroblasts to stimulate macrophage infiltration." (PMID 30567565, 2018). "Given that PC patients have the highest frequency of weight loss than those with other common cancers, our primary objective in this study was to explore the association of CC status with the serum IL-1β, IL-6, IL-8, or TNF-α levels in patients with resected or locally advanced PC." (PMID 30513776, 2018). "Although soluble tumor necrosis factor-α (sTNF-α) has been implicated in mediating drug-resistance in human cancers, whether transmembrane tumor necrosis factor-α (tmTNF-α) plays a role in chemoresistance remains unclear." (PMID 29559745, 2018). "However, interestingly, upon comparative analysis of the data on the TNF-α-308 AA and GG genotypes, the AA genotype was associated with a low overall survival rate of cancer patients, compared with patients with the GG genotype (AA/GG)." (PMID 30407345, 2018). "In August 2009, the US Food and Drug Administration (FDA) announced through a boxed warning that an increased risk of certain cancers in children might occur, and labeling for the tumor necrosis factor (TNF) blocker products was updated." (PMID 30587248, 2018). "TAM activation or macrophage polarization by inflammatory cytokines (IFN-γ, TNF, and IL-12), anti-inflammatory cytokines (IL-4 and IL-10), or bacterial lipopolysaccharide (LPS) is the primary process involved in inflammation-associated cancers." (PMID 30060484, 2018). "TNF-α is a cytokine implicated in systemic inflammation and cancer cachexia." (PMID 30482179, 2018). "TNF-α was thought to be associated with various malignant diseases, including cancer." (PMID 28575042, 2017). "This activation is associated with a release of the pro-inflammatory cytokine TNF-α, which could lead to a pro-inflammatory environment propitious for cancer development." (PMID 28632155, 2017). "Further, despite the absence of adaptive immunity, splenic tissue from orthotopically engrafted mice demonstrated elevations in several pro-inflammatory cytokines associated with cancer cachexia, including TNFα, IL1β, IL6 and KC (murine IL8 homologue), when compared to controls." (PMID 27901481, 2017). "TNF-α is an important multifunctional pro-inflammatory cytokine, which is closely linked to the occurrence, progression, metastasis, prevention and therapy of many types of human cancer." (PMID 28881857, 2017). "There are few studies that address cancer risk with the use of other (non-TNF inhibitor) bDMARDs." (PMID 29246243, 2017). "Conversely, cancer cachexia is associated with an increase in blood levels of C-reactive protein, cytokines (interleukin 1b, interleukin-6, TNF-α, and leukemia inhibitor factor, LIF) and other tumor derived factors like lipid mobilizing factor (LMF) and protein mobilizing factor (PMF)." (PMID 28337150, 2017). "Molecular epidemiological research suggests that TNF-α T-857C (rs1799724) polymorphisms may be associated with an increased risk of cancers, but results remain controversial." (PMID 28115787, 2016). "In a Swiss registry, malignancy risk was higher in elderly users of TNF inhibitors, but other observational studies showed that there was no increase in the risk of malignancy in elderly patients treated with TNF inhibitors." (PMID 27507033, 2016). "However, cancer therapy with systemically administered recombinant human TNF is associated with severe side effects due to TNF-mediated inflammation and toxicity." (PMID 27148266, 2016). "Therefore, genetic polymorphisms of TNF-α gene have been supposed as candidate risk factors of cancer." (PMID 28115787, 2016).
cancer (continued). "Cancer-associated fibroblasts secrete high levels of pro-inflammatory cytokines, including IL-1β, IL-8, IL-10, tumor necrosis factor-alpha (TNFα), monocyte chemoattractant protein-1 (MCP-1/CCL2), SDF-1/CXCL12 and interferon-beta (IFN-β), which have a range of effects on the immune system." (PMID 26828520, 2016). "Several miRNAs such as miR-155 and miR-21 have been implicated in cancer development and inflammation, and they are controlled by inflammatory mediators, the most prominent being Toll-like receptors (TLRs), TNF, TGF-β, and other cytokines that link the functions of miRNAs with inflammatory events." (PMID 26563372, 2016). "Here we have used a systems biology approach, integrating genomic and proteomic analyses, to determine a hierarchy of critical mediators and pathways associated with the TNF network that could be targeted in cancer." (PMID 26871292, 2016). "Elevated TNF-α was previously reported to have an important role in the depressed appetite symptomatic of infections and in conditions associated with disease such as cancer cachexia." (PMID 27007156, 2016). "Furthermore, in retrospective case control studies, the risk of cancer recurrence in RA patients treated with TNF inhibitors was similar to that for TNF-naïve patients." (PMID 27738754, 2016). "High plasma TNFα levels in cancer patients are associated with a poor disease outcome." (PMID 26112140, 2015). "The overexpression of FOS and TNF fixed the fate of the system as they can activate important genes implicated in the regulation of process of adhesion, apoptosis, immune response, cell proliferation and other signaling pathways related with cancer." (PMID 26088082, 2015). "However, the wideexpression of TNF receptors in the immune system and the downstream NF-κBstimulation signals caused uncontrollable hyperpyrexia when TNF-α was usedas an anti-angiogenic agent in cancer treatment." (PMID 25897826, 2015). "The relationship between TNF-α inhibitors and the risk for malignancy is hard to establish, given that most patients on this treatment are inherently predisposed to certain forms of cancer due to their underlying disease." (PMID 25815013, 2015). "TNF-α inhibitors might impact the risk of cancer development, or modify the risk of recurrence of previous cancers." (PMID 26253105, 2015). "In humans, data regarding the role of TNF-α in cancer-associated wasting are controversial." (PMID 26508820, 2015). "This energy wasting effect is commonly seen in both infections and cancer in all organisms, leading to cachexia that has been associated with elevated TNF levels and may respond to anti-inflammatory therapy." (PMID 25948885, 2015). "Similarly, increased levels of pro-inflammatory cytokines like tumor necrosis factors (TNF) and interleukin 1 (IL-1), caused by dysfunction of hypothalamic serotonergic neurons, have been implicated in cancer cachexia." (PMID 26668061, 2015). "However, selenium can also act through modulating the effect of TNF-α via TNF-α receptors and can up-regulate production of TNF-α in individuals in whom it is under-produced for example individuals at risk of carcinoma." (PMID 26445882, 2015). "Our meta-analysis emphasizes that genetic variation plays a crucial role in cancer; the TNF-α-308G>A polymorphism might play a role in a specific subtype of NHL and its importance may vary in different populations." (PMID 24857911, 2014). "Second, excessive sitting time could increase levels of inflammatory factors such as tumor necrosis factor-α, interleukin-6, and leptin which are known risk predictors for cancer." (PMID 25153314, 2014). "The association between cancer risk and other TNF-α antagonists needs further analysis." (PMID 25267341, 2014). "In addition to its role in HNSCC development by preventing TNF-induced apoptosis, specific cancer-associated missense mutations have been recently shown to induce NF-κB activation, a well-established pro-oncogenic player in HNSCC." (PMID 25275298, 2014).
cancer (continued). "The presence of DNA sequence variations in the regulatory region might interfere with transcription of the TNF gene, influencing the circulating level of TNF and thus increasing susceptibility to human diseases, such as cancer." (PMID 25420786, 2014). "Studies in mouse models show that NF-κB and TNF-α are linked with cancer progression." (PMID 24734105, 2014). "Due to the important role of TNF-α in cancer development, common functional polymorphisms (rs1800629 and rs361525) in TNF-α have been examined extensively in many studies, but the results were inconsistent across populations, in particular the Asian population." (PMID 25010932, 2014). "Animal studies also suggest that TNF-α is involved in muscle loss in cancer cachexia." (PMID 24624094, 2014). "Polymorphisms located in TNF-a promoter region, such as 308G/A and 238G/A, could affect the risk of various types of cancer by regulating TNF-a production." (PMID 24404201, 2014). "Its production is induced by proinflammatory cytokines such as Interleukin-6 (IL-6), IL-8, and tumour necrosis factor alpha (TNF-α) and its levels have been positively correlated with weight loss, anorexia-cachexia syndrome, extent of disease, and recurrence in many cancer types including CRC." (PMID 23840958, 2013). "The role of TNF in human cancer biology is less clear and it has been hypothesized that TNF inhibition may increase the risk of malignancies, particularly with prolonged, continuous exposure to TNF blockade." (PMID 24225257, 2013). "Many experimental evidence indicates that TNF-α is associated with the survival of cancer cells." (PMID 24066693, 2013). "The presence of inflammatory infiltrate in cases of OED favors the transformation and invasion process when stromal TNF-α and NF-kB are overexpressed, as NF-kB activated by TNF-α during inflammation predisposes the lesion to transformation, functioning as a link between inflammation and cancer." (PMID 23833665, 2013). "Several single nucleotide polymorphisms (SNPs) in the promoter region of the TNF-α gene may have putatively functional changes and thus may affect an individual’s susceptibility to cancer." (PMID 23870134, 2013). "TNF-α and IL-1α have been together implicated in a NF-κB-mediated signal cascade that inhibited apoptosis and increased the proliferation of epithelial cells in human prostate preneoplasia and cancer." (PMID 23991210, 2013). "Therefore, the pathophysiological relevance of TNF-α-induced NF-κB activation is underlined in cancer study." (PMID 23864892, 2013). "Moreover, a relationship was found between some TNF-α polymorphisms and development of different types of cancer." (PMID 23133455, 2012). "In addition, cancer associated fibroblasts, inflammatory cells (especially type-2 macrophages) and cytokines (e.g., IL-1β, TNF-α and IL-6) have been shown to affect the regulation of autophagy in cancer cells through induction of a metabolic stress." (PMID 22974323, 2012). "Several evidences underline the key role of TNF-α as mediator of inflammation and cancer." (PMID 23905066, 2012). "Without considering these factors, it may lead to the failure to detect the role of TNF-α-238 polymorphism in cancer development." (PMID 21818296, 2011). "The down-regulated genes were associated with proteasome, tumor necrosis factor (inflammation), carnitine palmitoyltransferase1A (ageing), glycogen synthase kinase, glutathione S-transferase (cardiovascular disease), and Jun oncogene (cancer)." (PMID 21356098, 2011). "In particular, pro-inflammatory cytokines (e.g. IL-1 and TNF), can themselves affect cancer risk." (PMID 19099590, 2008). "Interestingly, both networks associated with TNF-α-specific genes (Networks 10 and 11) overlap and have as top functions cancer and cell death." (PMID 18267009, 2008).
cancer (continued). "Inter-individual variations in TNF-A levels have been attributed to polymorphisms, notably the A allele at -308 (G/A) position in the promotor region of the TNF gene, which has been associated with higher TNF-A transcription levels and an increased risk of several types of cancer." (PMID 19099590, 2008). "The cytokine TNFα is regarded to be at the apex of inflammatory responses, promoting angiogenesis, mobilization of neutrophils and escalation of inflammation, including cancer associated inflammatory reactions." (PMID 18698347, 2008). "This type of result has been found in other cancer studies of TNF polymorphisms." (PMID 12966432, 2003). "In addition, anti-TNF-α treatment caused serious side effects, including cancers and infections, indicating that universal suppression of TNF-α may compromise the normal function of the immune system." (PMID 40323267, 2025). "Similarly, a Danish registry following 43,419 IBD patients over a median of 8.2 years reported increased cancer risk with thiopurine monotherapy (adjusted hazard ratio [aHR] 1.36, 95% CI 1.17–1.57) and combination therapy with anti-TNF agents (aHR 2.49, 95% CI 1.64–3.78)." (PMID 41228267, 2025). "Moreover, anti-TNFα therapy might modulate the NF-κB pathway, which is involved in cell survival, and its dysregulation increases cancer risk." (PMID 40282506, 2025). "Thus, the correlation with the loss of RASSF1A expression and the loss of p16, IL-8 and TNFα together with biomarkers of inflammation could be an interesting panel to develop for the early detection of cancer." (PMID 40095546, 2025). "Exercise has been shown to have anti-inflammatory properties in animal models by increasing the expression of anti-inflammatory cytokines and potentially inhibiting TNF-α-induced lipolysis, which may attenuate the loss of adipose tissue observed in cancer cachexia." (PMID 40869331, 2025). "The binding of OTA to TNF may exacerbate chronic inflammation, a known risk factor for cancer." (PMID 40864064, 2025). "Furthermore, TNF‐α plays an important role in all key mechanisms via skeletal muscle loss, adipose tissue loss, alterations in carbohydrate, protein and lipid metabolism, IR, systemic inflammation in cancer cachexia." (PMID 39764565, 2025). "As Fc-engineered antibodies potentiated proinflammatory TNFα production and macrophages are known to be influenced by cytokines, we evaluated whether macrophage phenotype was altered by antibody variants in cocultures with cancer cells." (PMID 41128663, 2025). "GO enrichment analysis and KEGG analysis indicated that cancer cells_MMP7 were enriched in genes associated with humoral immune response, IL-17 signaling pathway, chemokine signaling pathway, and TNF signaling pathway, suggesting that cancer cells_MMP7 may be associated with the immune response." (PMID 41016944, 2025). "Furthermore, elevated TNFα might be linked to cancer and is related to the AG genotype of rs361525 TNFA polymorphism in that disease." (PMID 38051374, 2024). "IL‐17A and TNF synergistically induced the reprogramming of mesothelial cells towards a pro‐inflammatory mesenchymal phenotype, concomitantly with a loss of tight junctions and an impairment of mesothelial monolayer integrity, thereby promoting cancer cell adhesion." (PMID 38566518, 2024). "However, TNF-α is involved in a myriad of physiological processes, and systemically inhibiting it comes with several unwanted effects like immunosuppression, increased cancer risk, and others." (PMID 38727310, 2024). "Importantly, based on the evidence presented here, the net effect is that this ensuing localized build up in ROS activates cancer cell death and causes release of pro-inflammatory factors such as TNFα, IFNs, heme and danger signals shifting the balance in favor of the anticancer immune response." (PMID 36066649, 2023). "Furthermore, the increased risk of cancer could be due to other immunosuppressant drugs that are given together with TNF-α inhibitors." (PMID 36836166, 2023).
cancer (continued). "Similarly, the average vote of non-NFκB/TNF hallmark genes increases with their cancer prevalence." (PMID 37475016, 2023). "However, TNF-α can increase carcinogenesis by activating the Wnt/β-catenin signaling pathway, inducing mutations in oncogenes, and promoting angiogenesis in tumors, as well as the proliferation and invasiveness of cancer cells." (PMID 37185713, 2023). "Regarding cancer risk, during a median follow-up of 4.0 years, the incidence of cancers (excluding nonmelanoma skin cancer) was higher with the combined tofacitinib doses compared to a TNF inhibitor, with lung cancer being the most common cancer described in the tofacitinib group." (PMID 37835065, 2023). "Additionally, a high cancer risk has been found in individuals with elevated TNF-α levels." (PMID 35928364, 2022). "Several hormones and cytokines, such as leptin, ghrelin, interleukin (IL)-1β, IL-6, and tumor necrosis factor alpha, contribute to the inflammation-mediated loss of fat and muscle and actively participate in the homeostasis of muscle and fat tissues in patients with cancer." (PMID 35203597, 2022). "However, the introduction of TNF inhibitors has raised safety concerns about the risk of cancer." (PMID 35945635, 2022). "As a pro-inflammatory cytokine, TNF may be implicated in various inflammation-related cancers." (PMID 35337149, 2022). "Although anti-TNF therapies remain a cornerstone in the treatment of ADs, optimal management is needed to handle the serious associated issues, including the development and progression of cancer, underscoring the growing importance over controlling the immunoreaction." (PMID 36678712, 2022). "However, patients with unadjusted risk variables may still less be offered TNF inhibitors, lowering the cancer risk of TNF inhibitor users." (PMID 35945635, 2022). "The contributions of oxidative stress and inflammation toward muscle wasting in cancer cachexia may work in parallel, or indeed promote the action of one another, as cytokines, particularly TNF‐α, are associated with oxidative stress in skeletal muscle during cancer." (PMID 36251564, 2022). "Furthermore, the decrease of expression of inflammatory genes such as IL-β, IL-6, and TNF-α could provide protection from the injury caused by the carcinoma associated inflammatory response." (PMID 35163250, 2022). "The integrated pathway involving TGF-β/Snail with TNFα/NFκB may be the principal axis that associates cancer cells to their microenvironment during the EMT process and exerts a critical role in CRC development and prognosis, which results in a poor prognosis for patients." (PMID 34394377, 2021). "As previously explained, as cancer cells escape the final stage of immunoediting, the exhaustion of T-cells causes an immunosuppressive state due to the upregulation of pro-inflammatory factors by the immune system (i.e., tumor necrosis factor-α [TNF-α] and interferon-γ [IFN-γ])." (PMID 34725602, 2021). "However, when PTT induces necrosis of cancer cells, there is destruction of plasma membrane integrity to cause the release of damage-associated molecular patterns and inflammatory cytokines, such as tumor necrosis factor (TNF)-α, interleukin (IL)-1β, and IL-6." (PMID 33947395, 2021). "Hence, the depletion of AWP1 may accelerate the cancer-promoting potential of cells in association with TNF-α signaling and dependent on ROS/NF-κB activation." (PMID 33816268, 2021). "Interestingly, this score significantly correlated with many cancer hallmarks associated with immune response, including TNF-α signaling via NF-κB, IL2, and STAT5 signaling; IL6, JAK, and STAT3 signaling; inflammatory responses; IFNα response; and IFNγ response." (PMID 32988398, 2020). "Due to TNFα‘s role in the immune system as a factor that causes tumor necrosis and controls infections, it was thought that the use of TNFα inhibitors could unleash cancer development and/or grant susceptibility to them." (PMID 32391269, 2020).